GFAP (glial fibrillary acidic protein)
Diseases named in the same sentence as GFAP in open-access papers (continued):
Sharing a sentence is not in itself a finding about the gene and the disease.
Stroke (continued). "Notably, another study investigating changes within the SN observed an increase in expression of GFAP, as well as CD45-positive microglia, as early as 24 h following MCAo in mice, whereas neuronal death was not seen in the region until 6 days post-stroke." (PMID 34884906, 2021). "IL-6 IL-6 was co-expressed with glial fibrillary acidic protein (GFAP, astrocyte marker) but not with Iba-1 (microglia marker) or NeuN (neuron marker), indicating that the main cellular source of IL-6 is astrocyte during stroke recovery." (PMID 31133816, 2019). "These DCX+ cells, did not stain with either Ki67 or GFAP and a significant correlation was also found between infarct volume and the number of DCX positive cells within the SVZ (r = 0.77, P<0.001, n = 15) 7 days post-stroke." (PMID 24809543, 2014). "However, unlike the GFAP vector, the neuron-specific enolase (NSE) vector showed significant reduction of infarct volume in animals that received the rAAV vector (p = 0.0087) and more significant improvement in the sensory motor tasks at both 2 days and 5 days post stroke (p < 0.0001)." (PMID 34570349, 2022).
Alzheimer disease (271 papers, 2007 to 2026). A progressive, neurodegenerative disease characterized by loss of function and death of nerve cells in several areas of the brain leading to loss of cognitive function such as memory and language. "Hippocampal GFAP was associated with increased odds of Alzheimer's dementia and faster decline in global cognition, episodic memory, semantic memory, and perceptual speed." (PMID 42309988, 2026). "Neurofilament light chain, glial fibrillary acidic protein and phosphorylated-tau 181 levels were elevated in early-onset Alzheimer’s disease compared with other diagnostic categories." (PMID 39825484, 2025). "For instance, GFAP levels increased in response to acute or chronic exposure to Aβ plaques, which are associated with Alzheimer's disease." (PMID 41036445, 2025). "Clinical studies have demonstrated that GFAP holds promise both as a diagnostic and prognostic biomarker, including but not limited to individuals with Alzheimer's disease." (PMID 39289040, 2025). "Levels of neurofilament light chain, glial fibrillary acidic protein and phosphorylated-tau 181, apolipoprotein E genotype and late-onset Alzheimer’s disease polygenic risk scores were determined." (PMID 39825484, 2025). "The recent inclusion of interchangeable use of plasma and CSF GFAP as a marker of inflammation (category ‘I’) in the Alzheimer’s Association Workgroup criteria for diagnosis and staging of Alzheimer’s disease showcases its suggested diagnostic potential." (PMID 40346659, 2025). "In contrast, GFAP is a biomarker for reactive astrogliosis, which is associated with both preclinical and clinical Alzheimer’s disease (AD)." (PMID 40061357, 2025). "In healthy older individuals and adults with symptomatic Alzheimer’s disease higher serum levels of GFAP associated with worse memory performance." (PMID 40177583, 2025). "Higher plasma levels of NfL and GFAP have consistently been associated with a higher risk of all-cause dementia and Alzheimer’s disease dementia." (PMID 37530894, 2024). "Incorporating GFAP into a panel of biomarkers enhances diagnostic accuracy for Alzheimer’s disease by providing additional insights into astrocytic activation and neuroinflammation, which are critical aspects of the disease’s pathology." (PMID 39554381, 2024). "GFAP, a component of the cytoskeleton of astrocytes, is upregulated during reactive astrocytosis, which has been associated with pathological changes in Alzheimer's disease and other neurodegenerative diseases and dementias." (PMID 38581544, 2024). "In Alzheimer’s disease, high GFAP levels are linked to amyloid plaque load and neurofibrillary tangles, suggesting its potential in early diagnosis and disease monitoring." (PMID 39063050, 2024). "A recent systematic review of GFAP studies indicated associations between GFAP and a number of neurological diseases and disorders, including major depressive disorder as well as Alzheimer’s disease." (PMID 38204926, 2024). "Plasma GFAP is increasingly recognized as a valuable biomarker that can be integrated into the existing diagnostic framework for Alzheimer’s disease." (PMID 39554381, 2024). "In Alzheimer's disease and other neurodegenerative dementias, elevated levels of GFAP are present in both serum and CSF, and associated with reduced cognitive performance." (PMID 38581544, 2024). "We examined the bivariate relationships of WMH, amyloid beta 42/40, phosphorylated tau 217 and glial fibrillary acidic protein with age-residualized neurofilament light chain across Alzheimer’s disease diagnostic groups." (PMID 39403075, 2024). "This study was the first to demonstrate increased plasma GFAP levels in cognitively normal older adults at risk of Alzheimer’s disease." (PMID 39554381, 2024). "Plasma glial fibrillary acidic protein (GFAP) is an emerging biomarker of Alzheimer’s disease (AD), with higher blood GFAP levels linked to faster cognitive decline, particularly among individuals with high brain amyloid burden." (PMID 39580758, 2024).
Alzheimer disease (continued). "This cohort study evaluates the association of kidney function with risk of diagnosis of incident Alzheimer disease or dementia and with the blood biomarkers neurofilament light, phosphorylated tau, and glial fibrillary acidic protein." (PMID 36692879, 2023). "Reduced coupling is associated with an increase in plasma GFAP, a biomarker for astrocyte activation and a warning sign for potential impending cognitive decline and Alzheimer's disease." (PMID 37586871, 2023). "We examined the association of Alzheimer's disease (Aß42/40 ratio; pTau181), neuronal injury (NfL), and reactive astrogliosis (GFAP) biomarkers with MRI measures of myelin content and axonal density." (PMID 36762407, 2023). "Previous publications have already shown that GFAP is associated with CI (especially memory function) not only in Alzheimer's disease but also in chronic HF." (PMID 37151899, 2023). "Is kidney function associated with Alzheimer disease (AD) or other dementias or with dementia-related blood biomarkers (neurofilament light [NfL], phosphorylated tau181 [p-tau181], and glial fibrillary acidic protein [GFAP])?" (PMID 36692879, 2023). "In Alzheimer’s disease mice, GFAP and neuron loss increased and neuronal nuclei (NeuN) decreased significantly." (PMID 35668943, 2022). "The severity of Alzheimer’s disease pathology is associated with increased GFAP expression in CSF and the density of reactive astrocytes." (PMID 33578866, 2021). "Because GFAPδ specifically interacts with PS, and astroglial cells are equipped with PS, enhanced production of amyloid-β should be associated with GFAP overexpression in astroglial cells in Alzheimer’s disease." (PMID 34202359, 2021). "In contrast, both acute and chronic exposure to low doses of alcohol (0.5 g/kg) increased glymphatic clearance, due to decreased GFAP expression, reducing the risk of Alzheimer’s disease." (PMID 33212927, 2020). "GFAP has been reported to have a high sensitivity and specificity in traumatic brain injury, Alzheimer’s disease, and sepsis-associated encephalopathy." (PMID 32545416, 2020). "Astrocytes react to a variety of CNS pathologies, including age-associated neurodegenerative diseases such as Alzheimer’s disease (AD), by upregulating expression of the intermediate filament glial fibrillary acidic protein (GFAP)." (PMID 31947996, 2020). "Amyloid beta oligomers are hallmark biomarkers in the etiology of Alzheimer’s disease and induce inflammation characterized by interleukin-6 increase and GFAP upregulation." (PMID 31847143, 2019). "Moreover, GFAP displayed predictive value for risk of Alzheimer disease progression and cognitive decline." (PMID 40421099, 2025). "Our primary aim was to examine and compare plasma NfL and GFAP levels in the pre-diagnostic phase of multiple neurodegenerative diseases, including Alzheimer’s disease, parkinsonian syndromes, and ALS, investigating their associations with each other and with incident neurodegenerative diseases." (PMID 41206819, 2025). "Furthermore, after adjusting or combining with other markers, higher levels of plasma GFAP displayed predictive value for risk of the development of Alzheimer’s disease and cognitive decline." (PMID 40421099, 2025). "This review supports including GFAP in the diagnostic framework for Alzheimer’s disease." (PMID 39554381, 2024). "GFAP is the major structural protein of astrocytes, and higher levels of this protein have been implicated in neurodegenerative disorders characterised by astrogliosis including Alzheimer's disease, multiple sclerosis 126, 127 and cerebral vasculitis." (PMID 38282400, 2024). "The Western Blot analysis in this study reveals that chronic noise exposure is linked to elevated protein levels of GFAP, Iba-1, Aβ, and Tau S369 in the hippocampus, suggesting that such exposure may induce Alzheimer’s disease-like pathological changes." (PMID 39343514, 2024).
Alzheimer disease (continued). "Despite reactive astrogliosis being a common pathological hallmark in both frontotemporal dementia and Alzheimer’s disease, significant differences were observed regarding blood GFAP level suggest that astrogliosis may differ between these pathologies." (PMID 39554381, 2024). "In this study, plasma GFAP levels were compared between cognitively normal older adults at risk of Alzheimer’s disease with high PET-Aβ load (Aβ+) and those with low Aβ load (Aβ−) from the Kerr Anglican Retirement Village Initiative in Aging Health (KARVIAH) cohort (n = 134)." (PMID 39554381, 2024). "While GFAP alone reflects astrocytic activation and neuroinflammation, which are common across various neurodegenerative diseases, its diagnostic utility is significantly enhanced when used alongside with established Alzheimer’s disease biomarkers." (PMID 39554381, 2024). "However, the predictive role of cerebrospinal fluid (CSF) GFAP on future cognitive transformation and alterations in Alzheimer’s disease (AD)-associated CSF biomarkers in newly diagnosed PD patients has not been investigated." (PMID 37475029, 2023). "Starting at month-6, this upregulated protein set includes neuroinflammatory-related proteins like complement C4-B, glial fibrillary acidic protein, protein-arginine deiminase type-2, vimentin, and vitronectin that have long been associated with Alzheimer’s disease." (PMID 35944844, 2022). "Moreover, there is evidence that higher levels of CSF GFAP are associated with cognitive decline in Alzheimer’s disease patients at early stages of dementia and also correlate with the severity of dementia." (PMID 33578866, 2021). "Here, we took advantage of the glial fibrillary acidic protein (GFAP) promoter to preferentially enhance transgene expression near plaques composed of amyloid-beta peptides (Aβ), a hallmark of Alzheimer's disease (AD), in the TgCRND8 mouse model of amyloidosis." (PMID 31754385, 2019). "Expression of VIVIT in hippocampal astrocytes, using adeno-associated virus (AAV) vectors equipped with the human GFAP promoter Gfa2, improved synaptic strength and/or normalized synaptic plasticity in animal models of Alzheimer’s disease and traumatic brain injury." (PMID 30297999, 2018). "GFAP also related to regional hypometabolism and atrophy in regions known to be affected in Alzheimer's disease, though with a slightly different regional pattern." (PMID 41978790, 2026). "Several biomarkers, including ADRD (Alzheimer’s disease and related dementias) biomarkers (Ab, tau, NfL, and GFAP) and angiogenic factors (VEGF, Flt-1, Tie-2, PIGF, and FGF) have been associated with the development of dementia." (PMID 41306424, 2025). "A study in cognitively unimpaired Amyloid beta positive individuals has shown that serum levels of GFAP, can predict development of Tau pathology, which has the likelihood of progressing into Alzheimer’s disease with cognitive impairment." (PMID 40177583, 2025). "In a Phase IIa clinical trial, 3TC was found to significantly reduce levels of glial fibrillary acidic protein (GFAP) in cerebrospinal fluid of individuals with early Alzheimer's disease, suggestive of reduced neuroinflammation." (PMID 41235755, 2025). "Currently, both tau isoforms and GFAP are used in the prediction and diagnosis of neurodegenerative diseases, particularly Alzheimer disease, and S100B in mild traumatic brain injury guidelines." (PMID 40523276, 2025). "Similar sex differences, characterized by higher peripheral blood GFAP levels in females, have also been described in Alzheimer's disease, Parkinson's disease, and in traumatic brain injury." (PMID 40232501, 2025). "Neurofilament light chain (NfL) and glial fibrillary acidic protein (GFAP) are detected in blood samples from a variety of neurodegenerative conditions including late-onset Alzheimer’s disease, Lewy body disease and frontotemporal dementia." (PMID 39825484, 2025).
Alzheimer disease (continued). "Plasma levels of protein biomarkers glial fibrillary acidic protein (GFAP) and neurofilament light (NEFL) are key dementia biomarkers, but it is unclear how risk genes for Alzheimer’s disease (AD) influence levels of these biomarkers." (PMID 40061357, 2025). "This study’s results suggest that longitudinal changes in pTau217 and GFAP are promising blood-based biomarkers for early identification and monitoring of Alzheimer disease progression in individuals with SCD." (PMID 41335440, 2025). "GFAP/C3-positive astrocytes subpopulations have been reported in numerous brain samples from neurodegenerative disease patients such as Alzheimer's disease, multiple sclerosis, Huntington's disease, Parkinson's disease, and ALS." (PMID 40276039, 2025). "In patients with FTD, peripheral GFAP levels were consistently lower compared to those with Alzheimer’s disease (AD), as observed in plasma and serum across seven studies." (PMID 40305176, 2025). "Increased GFAP expression also occurs with neurodegeneration in Alzheimer’s disease and multiple sclerosis." (PMID 38495109, 2024). "Previous studies with highly selected participants have shown that peripheral GFAP and NfL levels are elevated in the pre-clinical phase of Alzheimer’s disease (AD) and dementia." (PMID 38735950, 2024). "In Alzheimer's disease, serum GFAP levels have demonstrated their predictive value for transitioning from mild cognitive impairment to dementia." (PMID 38581544, 2024). "Overall in this study, plasma GFAP showed strong performances, with AUCs ranging from 0.74 to 0.94, with the most consistent increases observed in Alzheimer’s disease." (PMID 39554381, 2024). "Our study provides comprehensive insights into the role of brain region-specific GFAP expression in Alzheimer’s disease using bulk mRNA sequencing and TMT-MS proteomics." (PMID 39580758, 2024). "In sum, our study demonstrates that region-specific GFAP expression in the brain significantly correlates with various clinical and pathological features of Alzheimer’s disease, particularly in the cortex." (PMID 39580758, 2024). "GFAP is suggested as a potential biomarker for different brain disorders, including neuroinflammation and neurodegenerative disorders, like Alzheimer’s disease and Parkinson’s disease." (PMID 39596085, 2024). "Elevated GFAP expression is likely involved in the pathogenesis of neurodegenerative diseases such as Alzheimer’s disease, Parkinson’s disease, and amyotrophic lateral sclerosis." (PMID 39611118, 2024). "In this study, GFAP showed similar performances to pTau-181 in distinguishing Alzheimer’s disease from CU (P < 0.001) and MCI (P < 0.001) individuals, with a strong correlation with Aβ status." (PMID 39554381, 2024). "GFAP is an important biomarker widely used in the diagnosis and research of neurological disorders, such as Alzheimer’s disease." (PMID 39611118, 2024). "In an Alzheimer’s disease brain, active caspase-3 cleaves GFAP at a unique DLTD266 site, generating about 30 and 20 kDa products." (PMID 38891912, 2024). "Growing evidence positions GFAP as a biomarker for Alzheimer’s disease with specificity and disease-correlation characteristics comparable to established clinical markers, such as Aβ peptides and phosphorylated tau protein." (PMID 39554381, 2024). "Their findings as aligned with previous cohort studies, showing that plasma GFAP was incrementally increased along the course of Alzheimer’s disease from preclinical and prodromal stages to Alzheimer’s disease dementia (P < 0.001)." (PMID 39554381, 2024). "Glial fibrillary acidic protein (GFAP), the signature intermediate filament of astrocytes, has been proposed as a potential biomarker in various neurodegenerative disorders including Alzheimer’s disease." (PMID 38539657, 2024).